SOX9 (SRY-box transcription factor 9)
Diseases named in the same sentence as SOX9 in open-access papers (continued):
Sharing a sentence is not in itself a finding about the gene and the disease.
tumor (continued). "Furthermore, RNAseq data from HNO223 tumor cell lines knocked down for SOX2 or SOX9 demonstrated that 11 genes present in clinical samples were also present in clones knocked down for SOX2 or SOX9." (PMID 38275880, 2024). "BRG1 inhibition has been observed to prevent panIN formation and block panIN-derived PDAs by inducing apoptosis.SMARCA4 binds to the SOX9 promoter and helps to initiate the transcription of SOX9.SOX9 has been shown to affect tumor proliferation, and SOX9 knockdown has a pro-apoptotic effect." (PMID 39697230, 2024). "Sox9 can upregulate ABCA12 lipid transporter to promote tumor stemness and chemotherapy resistance." (PMID 38978960, 2024). "SOX9 can act as either a proto-oncogene or a tumor suppressor gene depending on the type of cancer." (PMID 38254873, 2024). "Tumor cells with reduced SOX2 levels show increased expression of mesenchymal markers, which is accompanied by the loss of morphological characteristics of epithelial cells and an increase in SOX9 expression." (PMID 38275880, 2024). "Tumor suppressor miR-145 targets SOX9 and TWIST to prevent ovarian CSC formation." (PMID 38473318, 2024). "Taken together, omics analyzes presented in this study support the hypothesis that the inverse SOX2/SOX9 expression is involved in tumor progression and resistance to treatment." (PMID 38275880, 2024). "Another study reported that exosomal circCMTM3 directly binds to miR-3619-5p and targets the downstream SRY-box transcription factor 9 (SOX9) to promote the proliferation, migration, invasion, and angiogenesis of HUVECs, enhancing their survival capacity and inducing tumor growth." (PMID 39444611, 2024). "Here, we demonstrated that SOX9 plays an important role during tumor progression being highly expressed in cancer cells at the invasive front, but lower expression has been detected in cancer cells of the tumor core." (PMID 38275880, 2024). "Here, we showed that the suppression of SOX10 is sufficient to mediate the transition of OLC-like (SOX10-high/SOX9-low) to NSC-like (SOX10-low/SOX9-high) tumor phenotypes, in line with the roles of these transcription factors in determining cell-lineage identities during normal development." (PMID 39285246, 2024). "Additionally, they identified β-TrCP, a component of the SCF E3 ubiquitin ligase, as a latent SOX9-bound tumor suppressor." (PMID 38978960, 2024). "Moreover, SOX9 levels were correlated with ZEB1 expression as exemplified in the ZEB1high MM10 tumor." (PMID 38519642, 2024). "SOX9, another crucial factor in stem/progenitor cell development, contributes to tumor progression." (PMID 39372390, 2024). "Taken together, these results suggest that tumor cells under irradiation downregulate their SOX2 expression while upregulating their SOX9 expression, and this inverse regulatory tendency may phenotypically increase their resistance to radiation." (PMID 38275880, 2024). "This may suggest that DNMT1 and SOX9 are independently regulated under YAP1-driven HC-originated CCA tumor region, while the NRAS-SOX9-DNMT1 signaling cascade may be active in Akt-NRAS CCA tumor cells." (PMID 39273023, 2024). "Indeed, in a 3D Matrigel assay SOX2-silencing in a cancer cell line with concomitant SOX9 expression present a higher tumor-initiating capacity compared with control cells." (PMID 38275880, 2024). "On the other hand, miR-101-3p also inhibits GB proliferation, migration, and invasion in vitro as well as tumor growth in vivo, at least in part, by directly downregulating SRY-box transcription factor 9 (SOX9) TF, which, in turn, promotes the activity of the AKT, WNT, and BML1 pathways." (PMID 38473710, 2024). "Furthermore, SOX9 were previously reported to be able to promote cancer cell proliferation and tumor progression by directly activating stem cell-like signaling and inhibit cell differentiation." (PMID 37051535, 2023). "SOX9/SOX2/OCT4 are the key regulators of tumor stemness maintenance." (PMID 37143164, 2023).
tumor (continued). "The interaction between PGD2 and its receptor could regulate cAMP production and SOX9 expression, and then have influence on tumor development." (PMID 36725845, 2023). "Although Inha KO tumours are thought to be derived from Sertoli cells, unexpectedly, SOX9+ cells, normally marking Sertoli nuclei, were less abundant in tumour regions and very low in the severe tumours despite being readily detected in Inha KO ‘normal’ and TAT tubules." (PMID 37564373, 2023). "Notably, SOX9 overexpression or miR-497-5p inhibition led to recovery of tumor sphere formation ability." (PMID 37468993, 2023). "Knockdown of SOX9 reduced tumor growth and prolonged the disease-free survival of the mice." (PMID 37491298, 2023). "But whether SOX9 functions specifically as an oncogene or a tumor suppressor is a matter of some debate." (PMID 37919693, 2023). "In a similar fashion, SOX9 and SOX10 genes were expressed in the tumor mass, wherein Sox9-positive tumor cells were localized to the tumor rim and perivascular areas, while Sox10-positive tumor cells were limited to the tumor rim and rarely present in the inner area of the tumor." (PMID 38003507, 2023). "Additionally, the transcriptional start site of miR-135b-5p had potential binding sites for SRY-box transcription factor 9, and the stemness properties of tumor cells were more remarkable in HCC with the upregulation of miR-135b-5p." (PMID 36755690, 2023). "However, the role of SOX9 in mediating an immunosuppressive tumor microenvironment is still unclear." (PMID 37020558, 2023). "Interestingly, SOX9 has been characterized as an oncogene in several tumor types, but also shown to function as a tumor suppressor." (PMID 37468993, 2023). "Notably, we observed a reduced presence of double PanCK+-SOX9+ tumor cells in G3 Tert−/− mice with respect to Tert+/+ mice." (PMID 37085672, 2023). "Instead, most CRC tumor tissues displayed upregulation of SOX9 compared to matched normal mucosa." (PMID 37051535, 2023). "In our opinion, the immunopromotive and immunosuppressive effects of SOX9 on tumors may be attributed to the degree to which different tumor types act on the tumor microenvironment." (PMID 37020558, 2023). "In addition, the SOX9 protein expression level was assessed via western blot in eight pairs of tumor tissues." (PMID 36854894, 2023). "Last, JMJD1C knockdown and SOX9 knockdown phenocopy in the inhibition of OS tumor growth." (PMID 37491298, 2023). "Besides, Sox9 was found to participate in the regulation of tumor micro environment (TME) and epithelial-mesenchymal transition (EMT) pathway." (PMID 36854894, 2023). "SOX9’s tumor immunomodulatory role will be further elucidated in future experiments." (PMID 37020558, 2023). "SOX9 has been reported to be positively correlated to tumor size." (PMID 37546388, 2023). "Furthermore, IHC showed that the expression levels of Ki67 and SOX9 were downregulated in the orthotopic tumor tissues treated with circEHD2-ASO." (PMID 37481520, 2023). "These contrasting findings may be attributed to varied roles of SOX9 in tumors of different degree of differentiations, tumor stages, patient populations, or dose-dependent effects." (PMID 35221802, 2022). "Particularly, KRAS G12D had significantly higher tumor SOX9 than KRAS WT." (PMID 34919787, 2022). "Emerging evidence also suggests that SOX9 interacts with the tumor immune microenvironment." (PMID 36003340, 2022). "Moreover, the expression of CD44 and SOX9 increased according to tumor grade in the samples of patients." (PMID 35205666, 2022). "SOX9 is significantly higher in pooled tumor than matched mucosa." (PMID 34919787, 2022). "The correlation of SOX9 expression with tumor progression is controversial." (PMID 35221802, 2022). "Moreover, the high SOX9 expression was significantly correlated with the larger tumor size (OR = 0.67; 95% CI: 0.49–0.91; P = .01; I2 = 0%, P = .85)." (PMID 36123852, 2022).
tumor (continued). "Further characterisation by matched single cell RNA-sequencing of the same tumours revealed that BCL-xL and MCL-1 expression correlated with expression of neural stem cell markers NES, SOX2 and SOX9 and the degree of malignancy within the tumours (CNA gain chromosome 7), independently of cell cycle." (PMID 35473984, 2022). "Metastatic tumor cells of distinct developmental tumor stages exhibited differential sensitivities to NK cell surveillance in patient and mouse models in a SOX9-dependent resistance mechanism-dependent manner and displayed context-dependent adaptation and immune evasion as demonstrated by scRNA-seq." (PMID 36527157, 2022). "In tumor biopsies, SOX9 expression is generally elevated and correlates with poor prognosis." (PMID 35562901, 2022). "The present results may explain SOX9 overexpression is associated with poor prognosis in patients with GC, and suggest that SOX9 could contribute to tumor progression in GC." (PMID 36123852, 2022). "We observed CC3 and nuclear Sox9 staining to be mutually exclusive at the border of cell death/neutrophil-rich region, providing direct in vivo evidence that the CSCs were resistant to the most potent tumor-killing therapy in our screen." (PMID 35788566, 2022). "Several previous studies have shown that the increased expression of SOX9 in human tumor tissue may lead to a decrease in epithelial differentiation of cancer cells and the development of tumor-associated epithelial–mesenchymal transition (EMT)." (PMID 35884771, 2022). "Moreover, the reduction in tumor volume exerted by the gemcitabine was significantly lower in tumors overexpressing SOX9." (PMID 35205666, 2022). "However, SOX9 is a tumor suppressor in cervical cancer, endometrial carcinoma, melanomas, and some intestinal tumors." (PMID 35884771, 2022). "The co-expression of NR2F1 (a dormancy marker) and SOX9 (a dormancy and cancer stem cell marker) preferentially in SM tumor cells suggests that these cancer cells adopt both dormant and cancer stem cell properties, a unique biology associated with the SM process." (PMID 35110548, 2022). "Moreover, YAP was enriched at the promoter regions of several key factors involved in the stemness of tumor cells, such as SOX9, SMAD2/4, OLIG2, and MYC." (PMID 35322024, 2022). "MiR-1225-5p served as a tumor inhibitor in OS by downregulating Sox9." (PMID 35297315, 2022). "Similarly, confocal fluorescence IHC showed higher SOX9 in tumor compared to matched mucosa, with stronger SOX9 immunostaining in KRAS G12D and G12V tumors." (PMID 34919787, 2022). "Additionally, MAFB protein is expressed in the tissue of Dupuytren’s cord, and MAFB and Sox9 form a positive feedback loop that maintains cell stemness and tumor growth in vitro and in vivo." (PMID 35563428, 2022). "In NSCLC, TAMs would stimulate tumor metastasis via the TGF- inhibitor/SOX9 axis." (PMID 34781924, 2021). "The xenograft tumour tissue in previous study were stained with the same antibodies, showing that Sox9, β-catenin increased, and β-catenin could be observed in more cytoplasm and nuclei of the xenografts formed by HCT116CD133+CD44+ shCldn7." (PMID 34281572, 2021). "Sox9-Pten mice also had later tumor onset (11–13 months) as compared to Alb-Pten (8–9 months)." (PMID 34083580, 2021). "Furthermore, DDC treatment that induces liver injury also promotes tumor formation in the Sox9-Pten mice." (PMID 34083580, 2021). "We also discuss progress regarding the role of SOX9 in gynecological malignancy pathogenesis through its mediation of important mechanisms, including tumor initiation and proliferation, apoptosis, migration, invasion, chemoresistance, and stem cell maintenance." (PMID 34881182, 2021). "SOX9, which is expressed by such distinct tumor cells, is known to be a useful immunohistochemistry marker for detecting the ductal lineage of pancreatic tumors; moreover, it has been reported as an important transcription factor for chondrocyte differentiation." (PMID 34513702, 2021).
tumor (continued). "This might also have major implications in the targeting of tumor stem cells in TNBCs and our understanding of the role of Sox9 and Sox10 during development." (PMID 33985544, 2021). "However, 69.23% and 30,76% of non-invasive tumors presented low and high SOX9 tumor expression, respectively." (PMID 33736633, 2021). "Bioinformatics analysis revealed that SOX9 expression was associated with genes related to the extracellular matrix-receptor interaction pathway and extracellular matrix structure organization, indicating a potential role of SOX9 in regulating tumor microenvironment." (PMID 34778027, 2021). "By randomly assessing the potential target genes in the tumor samples, we have found that up-regulated SOX9, RASA1, CEP55 and MAP4K4, the target genes of miR-582, might play important roles in LUAD tumorigenesis." (PMID 33510968, 2021). "Furthermore, the expression of both mRNA and protein of SOX9 was significantly higher in tumor tissues than in paired adjacent tissues." (PMID 34881182, 2021). "SOX9 has been relatively well investigated in this type of tumor." (PMID 34881182, 2021). "We explored if SOX9+ cells are the tumor forming cells activated upon PTEN loss; and whether liver injury promotes the formation of tumors from these Pten-deleted SOX9+ cells." (PMID 34083580, 2021). "Besides, 54.54% of female patients expressed a low SOX9 level while 45.45% of them expressed a high level of SOX9 in tumor tissues." (PMID 33736633, 2021). "However, 26.66 and 73.33% of patients with macroadenoma showed low and high SOX9 tumor expression, respectively." (PMID 33736633, 2021). "SOX9 was observed to be expressed in the nuclei of thymic epithelial cells and tumor cells." (PMID 34778027, 2021). "Western blot analysis showed a marked increase in the levels of Sox9 S181 phosphorylation in SLK knockout tumor cell lines that was correlated with elevated Sox10 levels in these cells, suggesting increased Sox9 activity in SLK-null tumor cells compared to the control." (PMID 33985544, 2021). "Overexpression of SOX9 could inhibit the proliferation of CC cells in vivo and tumor formation of CC cells in vitro." (PMID 34881182, 2021). "Therefore, the expression and function of SOX9 alters in different human cancers mainly by regulating the activity of cancer stem cells (CSCs), and as a tumor suppressor under certain circumstances." (PMID 34881182, 2021). "The tumor-specific SE-associated genes were enriched in important pathways, such as chordate embryonic development (RUNX2, FOXA1), regulation of cell adhesion (RUNX1, SOX2 and VEGFA), and epithelial cell differentiation (SOX9, ELF3)." (PMID 34001209, 2021). "Furthermore, high levels of SOX9 are related to the tumor grade, poor prognosis, and poor survival of some types of cancer." (PMID 34881182, 2021). "Thus, treated pre-adipocytes are able to release exosomes carrying a high level of miR-140, which can affect nearby tumor cells by targeting the SOX9 pathway." (PMID 34359591, 2021). "Furthermore, in agreement with our result, PITX1 expression levels were positively correlated with SOX9 levels in tumor and normal skin tissues." (PMID 34526609, 2021). "Similarly, BMI1 restoration also increased the tumor growth capacity of SOX9 knockdown Panc-1 cells." (PMID 31941916, 2020). "Using the TCGA dataset, we found that higher SOX9 levels in tumor samples correlated with greater enrichment of the molecular signatures of normal ER− luminal cells and ER− tumors, in agreement with a previous study with a small number of tumor samples." (PMID 32521267, 2020). "Similarly, senescence induction by SOX9 silencing was significantly mitigated (over 50% reduction) by BMI1 restoration in tumor cells." (PMID 31941916, 2020). "Similarly to SOX9, the tumor progression driver SP1 is also a key factor for the induction of TGF-β during inflammation and its overexpression in Cyp51 knock-outs relates to EMT." (PMID 33182326, 2020).
tumor (continued). "p62 and SOX9 are overexpressed in both PCa and BCa patient tumor tissue, correlate with disease progression and treatment resistance, and support BCa and PCa tumor growth in vivo, indicating that these proteins are functional in cancer and clinically relevant." (PMID 31959131, 2020). "Furthermore, our data reveal that SOX9 silencing promotes that tumor cells undergo senescence and apoptosis." (PMID 31941916, 2020). "Moreover, we reveal that SOX9 controls the proliferative capacity of tumor cells and facilitates evading senescence." (PMID 31941916, 2020). "As Sox9 also has important roles in sex determination, pancreatic differentiation, and tumor formation, the quantification of Sox9 SUMOylation could impact these biological processes." (PMID 32070068, 2020). "In human non-small cell lung cancer, miR-592 functions as a tumor suppressor by targeting SOX9." (PMID 33520987, 2020). "Interestingly, the Sox9-GFPhigh cells exhibited a higher proliferation rate than other luminal cells, supporting their role in tumor initiation." (PMID 32521267, 2020). "Sox9 was expressed in several tumour cases, both at the protein and mRNA level." (PMID 32397255, 2020). "Given that cellular senescence constitutes a tumor-suppressive mechanism that restricts tumor progression, we explored whether SOX9 would mediate senescence evasion in cancer cells." (PMID 31941916, 2020). "Several signaling pathways have key roles in the regulation of cell survival within tumor tissues, for instance, Wnt/β-catenin signaling pathway, which in turn is regulated by SOX9 through two main mechanisms: ββ-catenin degradation and transcriptional activity inhibition." (PMID 32411238, 2020). "Moreover, by using IHC analysis, we found that the staining intensity of SOX9 was obviously weaker in the tumor sections of the siRNA pool group than in those of the si-NC group." (PMID 33520987, 2020). "The fact that SOX9 modulation impacted on the expression of BMI1 in tumor cells in vitro and in vivo, suggested that BMI1 could constitute an effector of the pro-tumoral activity of SOX9." (PMID 31941916, 2020). "Moreover, BMI1 re-establishment in SOX9-silenced tumor cells restored cell viability and proliferation as well as decreased p21CIPin vitro and tumor growth in vivo." (PMID 31941916, 2020). "Our work reveals that the SOX9 transcription factor acts as a determinant of the ER− LSPC fate and its upregulation enabled by loss of BLBC tumor suppressors contributes to lineage plasticity and the progression of benign lesions to invasive tumors during BLBC oncogenesis." (PMID 32521267, 2020). "Interestingly, BMI1 restoration completely abrogated the reduction of tumor growth elicited by SOX9 knockdown." (PMID 31941916, 2020). "We next examined if SOX9 could confer oncogenic properties of NB cells and performed in vitro colony formation assay and in vivo tumor formation." (PMID 32595833, 2020). "SOX9 may also act as a putative proto-oncogene, influencing tumor malignancy and aggressiveness, possibly via the activation of MMP13." (PMID 33076370, 2020). "Indeed, immunofluorescent microscopy detected proliferating DRPs were concentrated in NTL around the peripheral border of the tumor mass as Ki67+ SOX9+ cells (purple arrows), revealing a close spatial association of DRPs with tumor cells." (PMID 33173221, 2020). "Similarly, western blotting results showed that lncRNA DLEU2 suppression markedly decreased the protein level of SOX9 in tumor tissues compared with the NC group." (PMID 31541993, 2019). "Another way to enhance the EMT by SOX9 is the loss of ZFP36 expression, a tumor suppressor." (PMID 31057614, 2019). "SOX9 overexpression was commonly observed in HCC with high tumor stage and tumor grade tissues." (PMID 31057614, 2019). "SOX9 enforced expression into murine prostate-induced tumor formation." (PMID 31366128, 2019). "SOX9 tumour suppressor activity could be due to the modulation of the Wnt/β-catenin signalling pathway." (PMID 31275454, 2019).